EGFR (epidermal growth factor receptor)
Diseases named in the same sentence as EGFR in open-access papers (continued):
Sharing a sentence is not in itself a finding about the gene and the disease.
breast carcinoma (continued). "EGFR is a direct target of miR-206 in breast cancer and the latter is induced in nuclear factor (erythroid-derived 2)-like 2 (NRF2)-deficient breast cancer." (PMID 29455658, 2018). "Overexpression of epidermal growth factor receptor (EGFR) and tumor hypoxia have also been shown to correlate with worse outcomes in several types of cancers including breast cancer." (PMID 30347860, 2018). "In human breast cancer, H19 lncRNA-derived miR675 targets c-Cbl and Cbl-b, E3 ubiquitin ligases which are known to degrade EGFR and c-MET thereby increases the stability of latter." (PMID 29455658, 2018). "Human epidermal growth factor receptor 2 (HER-2) is a member of epidermal growth factor receptor (EGFR) family, which is overexpressed in breast cancer, ovary cancer, uterine endometrioid carcinoma, gastric carcinomas, glioblastomas, etc." (PMID 30799657, 2018). "Collectively, these data demonstrate that knockdown of Akt1 prolonged EGFR activation through inactivating PIKfyve in breast cancer cells." (PMID 30445978, 2018). "GPER activation can stimulate Src-related tyrosine kinase activity-dependent EGFR transactivation and then cause ERK1/2 phosphorylation in breast cancer cells." (PMID 29360846, 2018). "Over-expression of miR-539 suppressed breast cancer cell proliferation and migration by reducing EGFR expression." (PMID 29391441, 2018). "Our results suggest that ADAMTS9 is a TSG epigenetically inactivated in breast cancer, which functions through blocking EGFR‐ and TGFβ1/TβR(I/II)‐activated AKT signaling." (PMID 29193730, 2018). "Several studies have revealed a role of EGFR in malignant tumor development and progression of the disease in canine mammary tumors." (PMID 30373614, 2018). "A recent study has revealed that autophagy regulates enrichment of ALDH+ve cancer stem-like cells via EGFR/Stat3 signaling in PyMT murine mammary cancer." (PMID 29455658, 2018). "In contrast, metastatic breast cancers (BC) derived from EGFR-expressing mammary tumors are inherently resistant to EGFR-targeted therapies." (PMID 30250119, 2018). "These experimental findings are supported by clinical studies that report high expression of EGFR in primary mammary tumors is predictive for reduced patient survival." (PMID 30250119, 2018). "We show here that both the MUC1 extracellular and intracellular domains contribute to EGF-induced EGFR activation in human colon and breast cancer cells with the predominate contribution from the MUC1 extracellular domain." (PMID 28731466, 2017). "Of note, it is known that detachment of non-malignant breast epithelial cells triggers lysosmal degradation of an ErbB2 signalling partner EGFR and that ErbB2-induced Mek activation prevents this degradation in detached breast cancer cells." (PMID 29285258, 2017). "Previous studies demonstrated that in contrast to EGFR or HER2 overexpressing breast cancer lines, the BxPC3 pancreatic cancer cell line is refractory to DDAs." (PMID 28423644, 2017). "The EMT inducible MDA-MB-468 breast cancer cells are a PTEN mutant cell line with high levels of EGFR expression." (PMID 29123322, 2017). "To investigate therapeutic effect of miR-338-3p on breast cancer lung metastasis experimentally, we injected 4T1 cells stably expressing firefly luciferase and EGFR or empty vector via mouse tail vein." (PMID 28703807, 2017). "At the molecular level, IGFBP3 activated SphK1 and led to S1P-dependent transactivation of EGFR in normal mammary epithelial and breast cancer cells." (PMID 29108245, 2017). "ADAM12 supports the CSC phenotype in claudin-low breast cancer cells via modulation of the EGFR activation." (PMID 28148288, 2017). "Human EGFR is overexpressed in nearly all subtypes of breast cancer; however, it is more frequently overexpressed in triple-negative or basal-type breast cancers, which are highly aggressive and resistant to existing therapies." (PMID 29100426, 2017).
breast carcinoma (continued). "For example, in luminal A breast cancer, EGFR and FOXC1 had 453 and 343 ceRNA connections, respectively and shared four miRNAs (miR-15b-3p, miR-141-3p, miR-200a-3p and miR-760)." (PMID 28052038, 2017). "miR-338-3p inhibition or EYA2 knockdown greatly attenuated the ability of EGFR to enhance breast cancer cell migration and invasion." (PMID 28703807, 2017). "For instance, higher cytokeratin-7 (CK7) and epidermal growth factor receptor (EGFR) expressions (4- to 8-fold) in cancer cells have been found in lung and breast cancer patients, whereas normal leukocytes are present in a very low level of expressions." (PMID 28645267, 2017). "Lapatinib, a dual inhibitor of EGFR and ErbB2 tyrosine kinases, induced autophagic cell death in ErbB2 overexpressing breast cancer cells, human hepatoma cells, and acute myeloblastic leukemia." (PMID 28338617, 2017). "When tumors were classified according to their basal nature using basal cell markers (CK5/6 and EGFR), basal-like breast cancer had significantly higher nuclear and cytoplasmic BRCA1 H-score (p<0.0001) and lowered N/C ratio than the non-basal tumors." (PMID 28863181, 2017). "For an initial training test of this pipeline, we sought to predict the sensitivity of breast cancer cells to dual HER2/EGFR inhibitors by using sensitivity data for neratinib and lapatinib." (PMID 28649435, 2017). "CTX-III inhibits the EGF-induced EMT in breast cancer cells, reducing EGFR phosphorylation and activation PI3K/Akt and ERK1/2." (PMID 29189742, 2017). "The receptor tyrosine kinases (RTKs) EGFR and HER2 have been widely associated with breast cancer (BC) pathogenesis." (PMID 29113345, 2017). "Herein, we review the outcomes of EGFR-targeted clinical trials in breast cancer and explore our current understanding of EGFR signaling within primary mammary tumors and how these events are altered in the metastatic setting." (PMID 28435746, 2017). "Overexpression of EGFR was reported in 15-20% of all breast carcinomas and in 50-70% of triple negative breast cancers (TNBC)." (PMID 28038470, 2017). "The second receptor, epidermal growth factor receptor (EGFR) is observed to be over expressed in all subtypes of breast cancer." (PMID 28415766, 2017). "Transfection of miR-206 repressed c-MET/EGFR levels in ovarian, renal, colorectal, and breast carcinoma cells." (PMID 29291022, 2017). "In conclusion, both IL-6 and EGFR promote breast cancer through STAT3 abnormal activation and predict a poor prognosis." (PMID 27861147, 2017). "The EGFR scores were calculated based on the gene expression profiling of MCF-7 breast cancer cells overexpressing EGFR." (PMID 28148288, 2017). "Since EGFR is upregulated in ERα- breast cancer subtype, EGFR inhibitors have been used as a possible therapeutic option." (PMID 27213582, 2017). "EGFR overexpression is associated with prognostic and predictive value in HER2-positive breast cancer patients." (PMID 28881584, 2017). "Epidermal growth factor receptor (EGFR) expression is an important marker in breast carcinoma pathology and is considered a pivotal molecule for cancer cell proliferation, invasion and metastasis." (PMID 28465354, 2017). "Here, we examined the importance of ECM in the cross-talk between ERs/IGF-IR/EGFR in breast cancer cell aggressiveness." (PMID 28079144, 2017). "By analyzing samples from 313 breast cancer patients, we found that EGFR is a first clinicopathological parameter positively correlating with PHD2." (PMID 28038470, 2017). "Apt-QLs delivered siRNA molecules labeled with fluorescein isothiocyanate (FITC-siRNA) more efficiently to EGFR-positive MDA-MB-231 breast cancer cells (MFI 185) than to EGFR-negative MDA-MB-453 breast cancer cells (MFI 21)." (PMID 28842588, 2017).
breast carcinoma (continued). "The use of breast cancer cell lines ectopically expressing EGFR or HER2 and pharmacological probes of UPR revealed all three DDA responses: HER1-3 downregulation, Akt dephosphorylation, and UPR activation, contribute to DDA-mediated cytotoxicity." (PMID 28423644, 2017). "Taken together, these data suggest that EGFR increases breast cancer cell proliferation through the miR-338-3p/EYA2 pathway." (PMID 28703807, 2017). "Two cell lines, MDA-MB-231 and Michigan Cancer Foundation-7 (MCF-7), were selected as breast cancer cells, with two kinds of membrane protein, epithelial cell adhesion molecule (EpCAM) and epidermal growth factor receptor (EGFR), observed in both cells." (PMID 29257118, 2017). "To further investigate the interaction between NO and EGFR in basal-like breast cancer, we first examined the effect of DETA/NO on cyclooxygenase-2 (COX-2) expression, which is implicated in tumor progression and poor outcome in ER negative breast cancer." (PMID 29113326, 2017). "EGFR also contributes to the development and progression of breast cancers and is overexpressed in approximately 50% of the Triple-Negative Breast Cancers (TNBCs) that lack Estrogen Receptor (ER), Progesterone Receptor (PR), and HER2." (PMID 28423644, 2017). "CXCR4 has been described to transactivate EGFR in breast cancer cells and in ovarian cancer cells in which it leads to both mitogen-activated protein kinase and AKT activation." (PMID 28423060, 2017). "Similar to our results for HER2, HER3 and EGFR have been reported to be upregulated in breast cancer cells after long-term treatment with the HER2-targeting antibody trastuzumab." (PMID 28881753, 2017). "Tumor growth and invasion in breast cancer gland xenograft models require thrombin-induced interplay between ErbB and EGFR, or by MMP-1-induced fibroblasts derived Ca2+ signaling." (PMID 29291033, 2017). "The Her2 receptors in breast cancer heterodimerize typically with epidermal growth factor receptor (EGFR) family members upon activation." (PMID 28446206, 2017). "Clinically, miR-338-3p expression negatively correlates with the expression of EGFR and EYA2, and low miR-338-3p levels and high EYA2 levels associate with breast cancer lung metastasis." (PMID 28703807, 2017). "One study has examined that modified exosomes can be used to transfer nucleic acid drugs such as let-7a to epidermal growth factor receptor (EGFR)-positive breast cancer cells." (PMID 28402944, 2017). "It is clear that more than two third of breast cancers express EGFR abnormally, and 90% of pancreatic cancer patients, of which the 5-year survival rate is less than 5%, overly express EGFR or it's ligands, such as TGFα and EGF." (PMID 28445134, 2017). "Therapy of colon and breast cancer with anti-EGFR and anti-ERBB2 antibodies, respectively, and of EGFR mutated lung adenocarcinoma with tyrosine kinase inhibitors is well established." (PMID 27844328, 2017). "In ERα-positive breast cancer cells, expression levels of syndecan-2 are controlled through the EGFR signaling pathway, in contrast to syndecan-4 where the expression is regulated by IGF-IR signaling." (PMID 28079144, 2017). "TS function of miR-147 was also described in breast cancer, where it targets EGFR-driven cell cycle network proteins and inhibits cell cycle progression and proliferation." (PMID 27730344, 2017). "Nevertheless, it is a plausible scenario that loss of ZNF516 expression would lead to the up-regulation of EGFR during breast cancer carcinogenesis." (PMID 28947780, 2017). "In agreement with the results presented in this manuscript, increased HER3 abundance and ErbB heterodimers after EGFR-targeted therapy has been shown for breast cancer patients." (PMID 28032592, 2017). "Recently, a series of CAR-NK-92 cell lines were generated, including CD3-CAR-NK-92 for peripheral T-cell lymphomas (PTCLs), EGFR-CAR-NK-92 for breast cancer, and CD138 or CS1-CAR-NK-92 for multiple myeloma (MM)." (PMID 28415754, 2017).
breast carcinoma (continued). "We found that expressions of alpha-smooth muscle actin (ACTA2) and signal transducer and activator of transcription 1 (STAT1) significantly increased with transient or stable overexpression of HER2 in EGFR-positive breast cancer cells." (PMID 28881584, 2017). "WT161 downregulated EGFR, HER2, and ER on breast cancer cells, associated with significant tumor growth inhibition both in vitro and in vivo in a xenograft mouse model." (PMID 29113288, 2017). "The relationship between the expression of miR-494-3p and EGFR in breast cancer cells will be further investigated." (PMID 29100291, 2017). "One of the targeted therapies is the Lapatinib, a dual tyrosine kinase inhibitor that interrupts the ERBB2 and EGFR pathway in the treatment of ERBB2 positive breast cancer, which is used as ditosylate and orally active." (PMID 28415602, 2017). "Altogether, our study is the first one to describe the relations between PHD2 and EGFR in both preclinical and clinical models of breast cancer." (PMID 28038470, 2017). "Taken together, these results suggest that WT161-triggered downregulation of EGFR and ERα in breast cancer cells is due to a post-transcriptional and HDAC6-independent event." (PMID 29113288, 2017). "miR-146a inhibits cell invasion in pancreatic cancer via inhibition of EGFR and NF-kB pathways, weakens the metastatic potential in breast cancer and reduces epithelial-mesenchymal transition of esophageal carcinoma." (PMID 29088784, 2017). "HER2 overexpression resulted in enhancement of ACTA2 and STAT1 expression in EGFR-positive breast cancer cells." (PMID 28881584, 2017). "We evaluated the applicability of the ASCO/CAP HER2 guideline criterion for breast cancer to assess the EGFR, HER2, c-MYC, and MET gene status." (PMID 28764718, 2017). "In conclusion, we show that CNR2 activation suppresses breast cancer through novel mechanisms by inhibiting EGF/EGFR and IGF-I/IGF-IR signaling axes." (PMID 27213582, 2017). "Through the miR-338-3p/EYA2 pathway, EGFR increases breast cancer cell growth, epithelial-to-mesenchymal transition, migration, invasion and lung metastasis in vitro and in a allograft tumor mouse model in vivo." (PMID 28703807, 2017). "In response to oleic acid, FFA1 has been shown to induce the activation of extracellular signal-regulated kinase 1 and 2 (ERK1/2) through a mechanism involving EGFR transactivation in a breast cancer cell line." (PMID 28747926, 2017). "Autoradiography of canine mammary carcinoma tissue sections was performed in order to confirm binding of 99mTc-DTPA-can225IgG to native canine EGFR in tissue." (PMID 29137329, 2017). "EGFR and HER2 are frequently overexpressed in breast cancer, and their dimerization is associated with more aggressive clinical behavior." (PMID 28881584, 2017). "The molecular crosstalk between hypoxia signaling and other major regulators of breast cancer pathogenesis, such as EGFR, is rather complex and multilayered." (PMID 28038470, 2017). "EGFR and ErbB2 receive particular attention in the context of breast cancer etiology and therapy because of their frequent overexpression and hyperactivation in breast carcinomas." (PMID 29156633, 2017). "In breast cancer cell lines, Ano1 activates the epidermal growth factor receptor (EGFR) and calmodulin-dependent protein kinase (CAMK) signaling pathways." (PMID 29156699, 2017). "CCND1, a protein related to cell cycle, was demonstrated to be involved in above EGFR-mediated G1/S transition,which contributed to the multidrug resistance in breast cancer cells." (PMID 29290947, 2017). "This study also aimed to characterize ErbB signaling events involved in early breast cancer development by comparative phosphoproteomic analysis of HMLECs triggered with EGFR and ErbB3-specific ligands in the context of ErbB2 overexpression." (PMID 28174229, 2017).
breast carcinoma (continued). "The steroid ligand,17b-Oestradiol (E2)is able to transiently up-regulate EGFR mRNA and protein both in human breast cancer cells and in the rat uterus." (PMID 28415812, 2017). "They identified miR-124, miR-147, and miR-193a-3p as tumor suppressors that can inhibit breast cancer proliferation by regulating the cell cycle network protein driven by EGFR." (PMID 29016617, 2017). "Epidermal growth factor receptor (EGFR) is overexpressed in all subtypes of breast cancer, particularly in IBC and triple-negative breast cancer." (PMID 28978083, 2017). "Among the downstream effectors of EGFR, PI3K and AKT activities are significantly increased in triple-negative (ERα-/PR-/HER2-) breast cancers, and PI3K expression is associated with poor prognosis in breast cancer." (PMID 29212252, 2017). "EGF activated STAT3 via gp130-independent EGFR and a strong correlation was found between nuclear STAT3 activation and EGFR expression in breast cancers through immunohistochemical analysis." (PMID 27861147, 2017). "Co-culturing macrophages and basal-like breast cancer cells upregulated the EGFR activity within the tumour cells as measured by the Picchu-FLIM EGFR sensor." (PMID 28166195, 2017). "It is known that breast cancers with high EGFR expression are more aggressive, larger in size and more likely to metastasize to the lymph nodes and brain." (PMID 28038470, 2017). "In breast cancer, the only approved therapy that targets EGFR is the oral tyrosine kinase inhibitor lapatinib." (PMID 29229933, 2017). "The mechanistic basis for the intratumoral heterogeneity of EGFR activity in this model of breast cancer was demonstrated to be related to the degree of macrophage infiltration in the tumour microenvironment." (PMID 28166195, 2017). "Time-dependant feedback HER3 activation after EGFR inhibition has also been proposed in the context of breast cancer, although these breast cancer cells already presented with HER3 phosphorylation at baseline." (PMID 28032592, 2017). "The aim of this study was to clarify the mechanism of breast cancer motility by EGFR and/or HER2 dimerization." (PMID 28881584, 2017). "DDAs are selectively cytotoxic to breast cancer cells that overexpress either HER2 or EGFR and EGFR overexpression potentiates DDA-induced Akt dephosphorylation." (PMID 28423644, 2017). "The current investigation describes for the first time a direct connection between the oxygen sensor PHD2 and EGFR as well as its subsequent signaling in breast cancer." (PMID 28038470, 2017). "Amplification of a locus hosting a proto-oncogene is a common oncogenic mechanism: the ERBB2 locus is amplified in breast cancer and EGFR in glioma multiforme." (PMID 28333948, 2017). "EGFR inhibitors such as gefitinib and laptinib have shown efficacy in other malignancies, but only moderate success in breast cancer, suggesting that an improved method of patient selection is required to identify those who would benefit the most." (PMID 28649643, 2017). "We found that when LOX was depleted in MDA-MB-231 breast cancer cells grown in standard plastic (2D) culture conditions, phosphorylation of several RTKs including the EGFR was reduced." (PMID 28416796, 2017). "We identify PHD2 as a novel contributor to EGFR signaling in breast cancer by describing its direct participation in the stability and activity of EGFR." (PMID 28038470, 2017). "Selective inhibition of erbB-2/EGFR-mediated signaling presents lapatinib as a promising drug to target erbB-2/EGFR-overexpressing breast cancers." (PMID 28061785, 2017). "It was previously shown that breast cancer cells engineered to overexpress EGFR are sensitized to DDA-induced cell death and Akt dephosphorylation, but differential sensitivity to DDA-mediated HER3 downregulation was not examined in that report." (PMID 28423644, 2017).